UBA1 (ubiquitin like modifier activating enzyme 1)
Description:
Catalyzes the first step in ubiquitin conjugation to mark cellular proteins for degradation through the ubiquitin-proteasome system. Activates ubiquitin by first adenylating its C-terminal glycine residue with ATP, and thereafter linking this residue to the side chain of a cysteine residue in E1, yielding a ubiquitin-E1 thioester and free AMP. Essential for the formation of radiation-induced foci, timely DNA repair and for response to replication stress. Promotes the recruitment of TP53BP1 and BRCA1 at DNA damage sites.
Synonyms: A1S9T; UBE1; UBE1X; POC20; CFAP124; A1S9; A1ST; AMCX1; GXP1; SMAX2; UBA1A; VEXAS
Tractability: PROTAC: UniProt records ubiquitination sites on it; ubiquitination databases record sites on it; its protein half-life has been measured; a small molecule that binds it is known.
Target class: Enzyme; Ligase
Chemical probes: ABPA3 (high quality), TAK-243 (high quality)
Gene: Protein-coding gene on chromosome X (47,190,713 to 47,215,173, forward strand). Ensembl gene ENSG00000130985.
Subcellular location: Cytoplasm; Mitochondrion; Nucleus; Nucleus (Isoform 1); Cytoplasm (Isoform 2)
Subcellular location (Human Protein Atlas): Nucleoplasm; Cytosol
Pathways (Reactome):
Disease: Dengue Virus Attachment and Entry
Immune System: Antigen processing: Ubiquitination & Proteasome degradation
Metabolism of proteins: Synthesis of active ubiquitin: roles of E1 and E2 enzymes
Gene Ontology:
Molecular function: protein binding; RNA binding; ubiquitin activating enzyme activity; ubiquitin-like modifier activating enzyme activity
Biological process: DNA damage response; protein ubiquitination; ubiquitin-dependent protein catabolic process
Cellular component: cytoplasm; cytosol; desmosome; endosome membrane; extracellular exosome; heterochromatin; lysosomal membrane; mitochondrion; nucleoplasm; nucleus; rough endoplasmic reticulum membrane
Homologues: Orthologues: chimpanzee UBA1 (99% identical), macaque UBA1 (99% identical), pig UBA1 (98% identical), guinea pig UBA1 (97% identical), rabbit UBA1 (97% identical), rat Uba1 (96% identical), mouse Uba1 (96% identical), dog UBA1 (94% identical), zebrafish uba7 (56% identical). Paralogues in human: UBA7 (44% identical), UBA6 (41% identical), UBA2 (15% identical), NAE1 (12% identical), UBA3 (11% identical), ATG7 (10% identical), SAE1 (10% identical), MOCS3 (9% identical), UBA5 (7% identical).
Diseases named in the same sentence as UBA1 in open-access papers:
UBA1 is named in the same sentence as 168 diseases in open-access papers, as found by Europe PMC text mining. Sharing a sentence is not in itself a finding about the gene and the disease. The quoted sentences say what the papers report.
VEXAS syndrome (102 papers, 2021 to 2026). An adult-onset inflammatory disease that affects only males and is caused by somatic, not germline, mutations. "Our study aimed to provide novel insights into the epidemiology of VEXAS syndrome in the United Kingdom, estimate its prevalence in related disorders and assess the pathogenic potential of rare UBA1 variants using genomic databases and patient cohorts." (PMID 40415210, 2026). "This is in keeping with previous reports showing that male patients with the pathogenic UBA1 mutations invariably exhibit disease manifestations in keeping with VEXAS syndrome." (PMID 40415210, 2026). "Somatic mutations in UBA1 are linked to VEXAS syndrome, a late‐onset inflammatory disorder with rheumatological and haematological features, primarily affecting elderly men." (PMID 40415210, 2026). "At the same time, WGTS enables the rapid implementation of new research findings into clinical diagnostics, as exemplified by the detection of UBA1 mutations associated with VEXAS syndrome." (PMID 41419605, 2026). "We determined the frequency of canonical and non‐canonical UBA1 variants and estimated the prevalence of VEXAS syndrome within these populations, and in overlapping conditions such as MDS and related myeloid disorders." (PMID 40415210, 2026). "To estimate the prevalence of VEXAS syndrome in the UK population, we interrogated two genomic databases and three genetic screening centres to identify cases with canonical UBA1 variants affecting the p.Met41 residue." (PMID 40415210, 2026). "Our findings highlight the importance of broader screening for both canonical and non‐canonical UBA1 mutations to improve understanding of VEXAS syndrome and its underlying mechanisms." (PMID 40415210, 2026). "Genetic testing confirmed a somatic UBA1 mutation, thereby establishing the diagnosis of VEXAS syndrome." (PMID 41704985, 2026). "Among individuals investigated for possible autoinflammatory disorders, the prevalence was nearly 1%, with 100% disease penetrance—every individual with a canonical UBA1 mutation was diagnosed with VEXAS syndrome." (PMID 40415210, 2026). "To provide a more comprehensive understanding of rare UBA1 variants and the prevalence of VEXAS syndrome across general and patient‐based populations, we leveraged data from existing UK‐based general population cohorts and a harmonized healthcare system." (PMID 40415210, 2026). "VEXAS syndrome is a rare, adult-onset autoinflammatory disorder caused by somatic mutations in the UBA1 gene." (PMID 41646962, 2026). "A prominent characteristic of VEXAS syndrome is systemic inflammation, which results from somatic mutations in the UBA1 gene, leading to myeloid and erythroid precursor dysfunction." (PMID 40563745, 2025). "In the bone marrow, UBA1 mutations associated with VEXAS syndrome can be detected in HSPCs, myeloid progenitors, lymphoid progenitors, and megakaryocytes; however, in the peripheral blood, these mutations are observed only in myeloid cells." (PMID 41178709, 2025). "VEXAS syndrome is a complex hemato-inflammatory disorder, driven by somatic mutations in the UBA1 gene within hematopoietic precursor cells." (PMID 39820409, 2025). "In this study, we describe a new human cell model of VEXAS syndrome, engineered by introducing the common M41V UBA1 mutation into the male monocytic cell line, THP1." (PMID 40588566, 2025). "VEXAS syndrome is a rare and severe systemic inflammatory disorder caused by somatic mutations in the X-linked UBA1 gene, primarily affecting men." (PMID 41394827, 2025). "In suspected cases of VEXAS syndrome, before bone marrow examination and UBA1 gene mutation study, a meticulous evaluation for biochemical parameters for nutritional deficiency, particularly megaloblastic anemia, is necessary." (PMID 41246582, 2025). "In VEXAS syndrome, UBA1 M41 mutations result in an isoform switch from UBA1b to a truncated, nonfunctional isoform, UBA1c." (PMID 40588566, 2025).
VEXAS syndrome (continued). "A genetic analysis revealed a Met41Leu mutation at the ubiquitin-activating enzyme 1 (UBA1) gene, confirming the diagnosis of VEXAS syndrome." (PMID 40130124, 2025). "A peripheral blood smear revealed vacuolated myeloid precursors, and targeted genetic testing identified a somatic pathogenic variant in the UBA1 gene (p.Met41Val), confirming the diagnosis of VEXAS syndrome." (PMID 40600106, 2025). "In VEXAS syndrome, the UBA1 mutation results in dysfunctional protein degradation, leading to the accumulation of misfolded proteins in myeloid and erythroid precursor cells, triggering cellular stress." (PMID 40563745, 2025). "VEXAS syndrome is a clinically heterogeneous inflammatory condition caused by mutations in the UBA1 gene." (PMID 40394087, 2025). "The molecular hallmark of VEXAS syndrome is somatic mutations in the hotspot region of methionine 41 (M41) in the E1 ubiquitin activating enzyme, UBA1." (PMID 40588566, 2025). "VEXAS syndrome (Vacuoles, E1 enzyme, X-linked, Autoinflammation, Somatic) is an adult-onset systemic autoinflammatory disease caused by somatic variants in the UBA1 gene located on the X chromosome." (PMID 41026267, 2025). "Of these, 20 patients (54%), all male, with a median age of 73 years (IQR 67–77), were diagnosed with VEXAS syndrome based on the identification of UBA1 mutations through next-generation sequencing (NGS)." (PMID 41409287, 2025). "Single-gene UBA1 testing showed somatic UBA1 mutation (p.Met41Thr variant), confirming the diagnosis of VEXAS syndrome." (PMID 40123786, 2025). "The genetic underpinning of VEXAS syndrome is linked to mutations in the UBA1 gene, located on the X chromosome, which encodes the enzyme responsible for initiating ubiquitin activation." (PMID 40563745, 2025). "At the molecular level, the pathophysiology of VEXAS syndrome is intricately associated with the dysregulated function of the UBA1 enzyme, leading to impaired protein homeostasis and abnormal activation of inflammatory pathways." (PMID 40869252, 2025). "In this case, the results of the initial biopsy were inconclusive; however, following repeat bone marrow biopsy and the diagnosis of MDS, VEXAS syndrome was confirmed with testing for UBA1 mutations." (PMID 40041629, 2025). "A diagnosis of VEXAS syndrome was established through genetic testing, which revealed variants in the UBA1 and DNMT3A genes following a collaborative multidisciplinary approach." (PMID 41450412, 2025). "This condition, termed VEXAS syndrome (Vacuoles, E1 enzyme, X-linked, Autoinflammatory, Somatic), is characterized by mutations at codon 41 of the UBA1 gene on the X chromosome, leading to impaired ubiquitin-activating enzyme 1 function." (PMID 40445522, 2025). "VEXAS syndrome (Vacuoles, E1 enzyme, X-linked, Autoinflammatory, Somatic) is a late-onset autoinflammatory disorder caused by somatic mutations in the UBA1 gene." (PMID 41409287, 2025). "VEXAS syndrome is a recently identified autoinflammatory disorder caused by somatic mutations in the UBA1 gene, leading to systemic inflammation and hematologic abnormalities." (PMID 40445522, 2025). "Systemic inflammation is a hallmark of VEXAS syndrome, yet the link between UBA1 mutations and inflammatory signaling remains poorly defined." (PMID 40588566, 2025). "He underwent genetic testing, which displayed a mutation in the UBA1 gene at Exon 3, c.122T > C (p.Met41Thr), and was thus diagnosed with VEXAS syndrome." (PMID 40650768, 2025). "This approach led to the identification of UBA1 mutations in three patients on the whole cohort, emphasizing the utility of a phenotype-driven strategy for detecting VEXAS syndrome within rheumatology practice." (PMID 41409287, 2025). "Tolerated or not tolerated and pathogenic or not pathogenic represent 2 key future questions to ask for individual UBA1 variant among the full spectrum of mutations identified in the available VEXAS syndrome cohorts." (PMID 40906528, 2025).
VEXAS syndrome (continued). "VEXAS syndrome (vacuoles, E1 enzyme, X-linked, autoinflammatory, somatic) results from somatic mutations in the UBA1 (ubiquitin-like modifier-activating enzyme 1) gene and is considered a prototype of acquired haematoinflammatory disease." (PMID 40943714, 2025). "VEXAS syndrome is caused by somatic mutations in the UBA1 gene, which encodes the E1 enzyme essential for the ubiquitination pathway." (PMID 40600106, 2025). "VEXAS syndrome, a rare autoinflammatory disorder characterized by somatic UBA1 mutations, systemic inflammation, and hematologic abnormalities, presents primarily in older males." (PMID 40563745, 2025). "The presence of vacuoles on biopsy raised suspicion for VEXAS syndrome, leading to testing for the UBA1 mutation." (PMID 40041629, 2025). "In March 2023, the patient’s genetic testing revealed a UBA1 gene mutation, solidifying a diagnosis of VEXAS syndrome." (PMID 40650768, 2025). "VEXAS syndrome, caused by somatic mutations in the UBA1 gene, leads to severe inflammatory conditions that manifest in adulthood." (PMID 40869252, 2025). "Once the patient’s condition improved, whole-exome sequencing revealed a UBA1 splice-site mutation (c.118-1G>C), consistent with VEXAS syndrome." (PMID 41394827, 2025). "VEXAS syndrome is an autoinflammatory disease caused by somatic mutations in the UBA1 gene, predominantly affecting older men." (PMID 41394827, 2025). "The most common mutations in VEXAS syndrome are UBA1 p.M41T, UBA1 p.M41V and UBA1 p.M41L, which affect methionine 41 of exon 3 and lead to isoforms of UBA1 with considerably reduced catalytic activity." (PMID 41077698, 2025). "The second biopsy ultimately confirmed the diagnosis of MDS, which then led to UBA1 mutation testing and, finally, the diagnosis of VEXAS syndrome." (PMID 40041629, 2025). "We engineered THP1 cells to express the second most common and most pathogenic UBA1M41V mutation, recapitulating key features of VEXAS syndrome, including aberrant vacuolization and dysregulated UBA1 protein expression." (PMID 40588566, 2025). "Although VEXAS syndrome is induced by a spontaneous somatic mutation in HSC UBA1 in humans, we report here the results of Cre/fl-based CKO models by observing the primary mutant mice or by transplantation of mutant bone marrow (BM) cells into chimeric mice." (PMID 40906528, 2025). "VEXAS syndrome is caused by somatic mutations in the ubiquitin-like modifier activating enzyme 1 (UBA1) gene located on the X chromosome, predominantly affecting adult males, and characterized by a variety of clinical manifestations." (PMID 40247386, 2025). "Genetic testing for UBA1 mutations confirmed the Met41Thr mutation in exon 3, establishing a diagnosis of VEXAS syndrome." (PMID 39820409, 2025). "VEXAS syndrome is characterized by a somatic mutation in the ubiquitylation UBA1 gene in blood cell precursors, which drives the disease process." (PMID 41450412, 2025). "VEXAS syndrome (vacuoles, E1 enzyme, X-linked, autoinflammatory, and somatic) is a recently identified clonal disorder caused by somatic UBA1 mutations in hematopoietic stem cells, leading to bone marrow failure (BMF) and systemic inflammation." (PMID 40846800, 2025). "Because of the failure of anakinra, the emergence of macrocytic anemia, and an atypical IgG monoclonal component for SchS, UBA1 sequencing was performed, revealing the p.Met41Thr mutation, thus establishing a diagnosis of VEXAS syndrome." (PMID 40448343, 2025). "VEXAS syndrome is an adult-onset autoinflammatory disease caused by somatic variants in the UBA1 gene, which are involved in protein ubiquitination, resulting in severe systemic inflammation and blood disorders, such as myelodysplastic syndrome." (PMID 40498270, 2025). "The diagnosis of VEXAS syndrome requires genetic testing to confirm somatic mutations in the UBA1 gene." (PMID 40563745, 2025).
VEXAS syndrome (continued). "Somatic mutations in methionine 41 (p.Met41val, pMet41Thr, and p.Met41Leu) of UBA1 were identified as causing VEXAS syndrome." (PMID 39982357, 2025). "Genetic testing confirmed a UBA1 mutation (c.121A > G, p.Met41Val), establishing the diagnosis of VEXAS syndrome." (PMID 40445522, 2025). "VEXAS syndrome and UBA1 pathogenic mutations are present in 1/4000 males over the age of 50 and represent a significant public health burden." (PMID 38360993, 2024). "VEXAS Syndrome is a recently discovered monogenic, adult-onset, autoinflammatory syndrome associated with loss-of-function mutations in codon 41 of UBA1, encoding E1- ubiquitin ligase." (PMID 39463879, 2024). "Next-generation sequencing (NGS) performed on peripheral blood revealed a pathogenic UBA1 mutation (p.Met41Thr), establishing the diagnosis of VEXAS syndrome." (PMID 39411287, 2024). "The functional impairment of UBA1 caused by mutations associated with XL-SMA is relatively minor when compared to VEXAS syndrome." (PMID 39347709, 2024). "VEXAS syndrome (Vacuoles, E1 enzyme, X-linked, Auto-inflammatory, and Somatic), first described in 2020, is a monogenic disease resulting from a mutation in the UBA1 gene." (PMID 39594638, 2024). "Myeloid lineage-restricted somatic mutations of the UBA1 gene affecting the Met41 residue were detected in all patients with VEXAS syndrome." (PMID 38212709, 2024). "Given the potential underreporting of VEXAS syndrome, we highly recommend contemporary screening for UBA1 mutations in patients presenting with ambiguous signs of systemic autoinflammatory symptoms which persist over 18 months despite treatment." (PMID 38398362, 2024). "Mechanistically, VEXAS syndrome arises from a somatic mutation in the UBA1 gene, primarily located at the p.Met-41 site." (PMID 39289602, 2024). "The goal of allo-HCT in VEXAS syndrome remains eradication of the UBA1 clone and the associated inflammatory and hematological disease." (PMID 39168911, 2024). "The results revealed a p.Met41Leu mutation in the UBA1 gene, confirming the diagnosis of VEXAS syndrome." (PMID 39251478, 2024). "VEXAS syndrome is a recently identified autoinflammatory disorder resulting from somatic mutations in the UBA1 gene, leading to a complex spectrum of severe inflammatory and hematologic manifestations." (PMID 39598114, 2024). "It is also crucial to note that the expression of VEXAS syndrome can vary widely, largely influenced by the specific UBA1 mutation involved." (PMID 39598114, 2024). "VEXAS syndrome is a recently described autoinflammatory syndrome caused by the somatic acquisition of UBA1 mutations in myeloid precursors and is frequently associated with hematologic malignancies, chiefly myelodysplastic syndromes." (PMID 38840907, 2024). "Patients with VEXAS syndrome carry mutated forms of the UBA1 gene, primarily affecting the bone marrow." (PMID 39598114, 2024). "VEXAS syndrome represents a unique intersection of genetic and inflammatory pathophysiology, primarily driven by UBA1 gene mutations." (PMID 39594638, 2024). "Through whole-genome or whole-exome sequencing, NGS enables researchers to quickly and comprehensively identify genetic variations associated with VEXAS syndrome, especially mutations in the UBA1 gene." (PMID 38167209, 2024). "UPR upregulation has been implicated in VEXAS syndrome, an autoinflammatory syndrome driven by somatic UBA1 LOF variants." (PMID 39403923, 2024). "Systemic corticosteroids are frequently administered empirically before the identification of the underlying UBA1 mutation and are considered a first-line treatment for managing the inflammatory symptoms and cytopenia associated with VEXAS syndrome." (PMID 39598114, 2024). "VEXAS syndrome was described in 2020 as an autoinflammatory disease caused by postzygotic variants in the UBA1 (Ubiquitin Like Modifier Activating Enzyme 1) gene, located on the short arm of the X chromosome." (PMID 38984133, 2024).